INS (insulin)
Diseases named in the same sentence as INS in open-access papers (continued):
Sharing a sentence is not in itself a finding about the gene and the disease.
Hypoglycemia (continued). "An orexinergic input to the DMV has also been implicated in the increase in pancreatic parasympathetic nerve discharge produced by insulin-induced hypoglycemia." (PMID 24616659, 2014). "It has been demonstrated that first insulinization with basal insulin is effective and safe with reduced AEs including hypoglycemia, in clinical trial, as well as real-world setting." (PMID 24528773, 2014). "Analyses of serum samples obtained at the time of hypoglycemia initially showed low insulin and C-peptide levels." (PMID 25541899, 2014). "The addition of DPP-4 inhibitors to ongoing insulin therapy is expected to reduce insulin dosage, leading to a reduction in the frequency of hypoglycaemia and/or weight gain." (PMID 24607023, 2014). "Studies on intensive insulin therapy point out the danger of hypoglycemia that occurs in up to 5% of patients and poses a severe complication." (PMID 25278226, 2014). "Insulin-induced hypoglycemia increases cfos activation in a number of hypothalamic nuclei, including the ARC, the paraventricular and dorsomedial nuclei and the lateral hypothalamus." (PMID 25540613, 2014). "In the insulin detemir group, nocturnal hypoglycaemia occurred at a rate of 0.07 and 0.25 events per patient year at baseline and at final visit, respectively." (PMID 25048824, 2014). "During episodes of severe hypoglycaemia, when i.v. insulin administration had been stopped, blood insulin concentrations were markedly elevated at 10 750 pmol/l, with appropriate C-peptide levels of <94 pmol/l." (PMID 24711924, 2014). "It is a well-established recommendation that patients reduce their pre-exercise rapid-acting insulin dose to prevent exercise-induced hypoglycaemia, and the metabolic implications of this are well known." (PMID 24858952, 2014). "In our two patients, demonstration of factitious hypoglycemia was accomplished by detection of high insulin levels using Architect and Advia Centaur insulin assays, which are electrochemiluminescence immunoassays as well." (PMID 25541899, 2014). "More recently, in vivo studies demonstrated that the counter-regulatory response to insulin-induced hypoglycemia is impaired in CB-resected dogs." (PMID 25360117, 2014). "During another symptomatic hypoglycemia, she had plasma glucose of 44 mg/dl while her plasma insulin and C-peptide were 49.81 miu/ml and 9.36 ng/ml respectively confirming endogenous hyperinsulinemic hypoglycemia." (PMID 24741994, 2014). "Meglitinides play a role by increasing insulin secretion but easily lead to hypoglycemia and weight gain, in addition to being expensive and having only short-term efficacy." (PMID 24633252, 2014). "Hypoglycemia usually occurs as a result of a mismatch between insulin dose, the amount of food consumed, and energy expended." (PMID 24616659, 2014). "In these studies, intensive insulin therapy significantly increased the incidence of severe hypoglycemia (blood glucose level ≤40 mg/dL); however, mortality was not reduced." (PMID 25705413, 2014). "We split patients into two groups according to their glycaemic condition at 2 h during the post-operative OGTT (post-load hypoglycemia/euglycemia) and compared the changes in glucose, insulin and C-peptide concentrations and respective AUC." (PMID 24736741, 2014). "Glucose sensing is essential for insulin-treated diabetic patients to counter-regulate insulin-induced hypoglycemia." (PMID 25360117, 2014). "In contrast to previous reports, we found GHR-KO mice on CR to beless responsive than theirad libitum (A.L.)counterparts to the hypoglycemia-inducing effects of insulin." (PMID 25789159, 2014). "This is compatible with the notion that SU should be used at low doses to prevent hypoglycemia due to inappropriate insulin secretion." (PMID 24578754, 2014). "Different types of stimulations, such as insulin-induced hypoglycemia, caffeine, and stress, have been shown to activate orexin neurons in the hypothalamus evaluated by measuring c-Fos expression in orexin neurons." (PMID 25162023, 2014).
Hypoglycemia (continued). "Insufficient suppression of insulin secretion in the presence of recurrent serious hypoglycemia is the basic characteristic of this condition." (PMID 24932607, 2014). "The present results further add to our understanding on incidence and predictors of hypoglycemia in insulin-naïve patients." (PMID 24528773, 2014). "On postpartum day 2, hypoglycemia (24 mg/dL) and hyperinsulinism (insulin level 15 mU/L) were detected." (PMID 24932607, 2014). "We report two cases emphasizing the importance of insulin assays for evaluation of hypoglycemia in diabetic patients." (PMID 25541899, 2014). "In man, hyperoxia attenuates the counterregulatory hormonal responses to insulin-induced hypoglycemia." (PMID 24616659, 2014). "As native insulinoma cell lines tend to produce insulin, which after inoculation in mice often leads to fatal hypoglycemia, we decided to use CHL cells that were transfected to overexpress the GLP-1 receptor in both in vitro and in vivo experiments." (PMID 25006548, 2014). "Correlations between the total and subscale scores were as follows: exercise, r = 0.27 (P = 0.02); hypoglycemia, r = 0.65 (P <0.01); diet, r = 0.72 (P <0.01); blood glucose test, r = 0.88 (P <0.01); and insulin dose, r = 0.62 (P <0.01)." (PMID 25960778, 2014). "Hypoglycemia was found to be connected to the time patients spend on the protocol (the longer the therapy, the higher the chance of hypoglycemia) making the strict monitoring of glucose levels even more important during intensive insulin therapy." (PMID 25278226, 2014). "Insulin dosages were appropriately skipped or tapered according to the amount of oral intake in unsuccessful attempts to avoid hypoglycemia during periods where hypoglycemia was observed." (PMID 24524438, 2014). "The use of sliding-scale insulin and basal-bolus insulin resulted in 10.1% and 2.5% cases of hypoglycemia, respectively." (PMID 25181406, 2014). "A reduction in glycated haemoglobin (HbA1c) and less hypoglycemia was shown in a previous study adding vildagliptin on top off an existing insulin regimen." (PMID 25175981, 2014). "The intensive insulin group had a higher rate of hypoglycemia than the control group (RR = 2.93, 95% CI [1.69, 5.06], P = 0.0001), and there was substantial heterogeneity across the trials (I2 = 61%, P = 0.02)." (PMID 25136614, 2014). "This is of particular interest because fears of hypoglycemia remains one of the key obstacles to both initiating and optimizing insulin therapy." (PMID 24620742, 2014). "Subjects using insulin to carbohydrate ratio also adjusted the ratio for unexplained hypoglycemia and a pattern of three high blood sugars." (PMID 25024710, 2014). "It is also important to emphasize that there is no doubt as to the fact that cognitive alterations occur during insulin-induced hypoglycemia." (PMID 24790575, 2014). "GLP-1 increases insulin and decreases glucagon secretion in a glucose-dependent manner, resulting in glucose lowering action with a low incidence of hypoglycaemia." (PMID 25419179, 2014). "Incidence of hypoglycemia in insulin-naïve group (1.1% [0.036 episodes/patient-years]) and insulin non-naïve group (0.6% [0.029 episodes/patient-years]) was similar to the overall incidence." (PMID 24528773, 2014). "There are several open questions about the management of insulinoma, including the correlation among insulin serum levels, control of the hypoglycemia, and tumor response." (PMID 25298880, 2014). "In the insulin-treated group, there were 7 cases of hypoglycemia lower than 4 mmol/l and 1 case occurred in the control group." (PMID 25278226, 2014). "β-Cell-specific expression of placental lactogen-I results in accelerated β-cell proliferation, increased β-cell mass and number and increased insulin production, leading to hypoglycemia and elevated plasma insulin." (PMID 25126749, 2014).
Hypoglycemia (continued). "Satisfaction will mean incorporation of information received into their daily routine of proper insulin use, proper dieting, optimal physical activity and avoidance of preventable complications such as hypoglycemia." (PMID 24397956, 2014). "There are also reports of self-inflicted cases of hypoglycemia due to frequent use of prime function on an insulin pump, which provides small insulin doses to clean the air within the tube and are not recorded in daily insulin history." (PMID 25541899, 2014). "In no case did any volunteer experience a biochemical or symptomatic hypoglycemia as a result of the endogenous insulin release in response to the large iv glucose bolus." (PMID 25144632, 2014). "Based on lower overall rates of minor hypoglycemia, reduced weight gain, and perceived convenience, the authors of this study recommended once-daily basal insulin as the first-line insulin therapy." (PMID 24620742, 2014). "The intraclass correlation coefficient between the baseline and 3-month scores on the DSMP was 0.99 (exercises, 0.99; hypoglycemia, 0.99; diet, 0.60; blood glucose test, 0.99; insulin dose, 0.97) and on the SCI-R it was 0.99." (PMID 25960778, 2014). "Outcomes assessed included HbA1c, the changes in fasting glucose levels, body weight, serum lipids values, insulin dose and symptomatic hypoglycemia." (PMID 24614911, 2014). "The data on hypoglycemia in patients receiving insulin other than glargine and switching to insulin glargine will be further elaborated in subsequent publication, which would include comprehensive results of effectiveness and safety in this cohort." (PMID 24528773, 2014). "This alteration correlated with the grade of insulin resistance of the subjects in the hypoglycemia setup." (PMID 24400077, 2014). "First, the counter regulatory hormonal responses to hypoglycemia induced by the insulin clamp technique in dogs are blunted in animals that have undergone carotid body resection." (PMID 25642193, 2014). "Insulin induced hypoglycemia is employed in the simultaneous assessment of the functional reserves of both the hypothalamic–pituitary–adrenal axis and the GH/IGF-I axis." (PMID 24723909, 2014). "Of additional interest, there was less weight gain and fewer episodes of hypoglycemia with MET than with SFU or insulin." (PMID 24524730, 2014). "A recent systematic review and meta-analysis of basal and premixed regimens demonstrated that twice-daily premixed insulin regimens reduced HbA1c by an additional 0.45% (CI 0.19–0.70%), but with additional weight gain and higher rates of hypoglycemia." (PMID 24620742, 2014). "Among diabetic patients treated with recombinant human insulin, antibodies created against exogenous insulin are also a common phenomenon and hypoglycaemia has been seen in cases where insulin antibodies are present in the circulation." (PMID 24711924, 2014). "Glargine insulin is a peakless, long-acting insulin analog that provides 24-h basal insulin replacement and achieve target HbA1C level with less hypoglycemia in most patients when it is added to existing OADs as a once-daily injection." (PMID 24614911, 2014). "Nevertheless, in that same study insulin-induced hypoglycemia produced a significant increase in cortisol response after L-T4 treatment." (PMID 25180035, 2014). "Assay with this ELISA showed results nearly identical to the immunobead assay, with insulin levels rapidly diminished in the LOW ferrets during hypoglycemia." (PMID 24594704, 2014). "The results of this study also demonstrate significant differences in cases of hypoglycemia (defined as blood glucose <3.3 mmol/L) between basal-bolus insulin and sliding-scale insulin regimens (p = 0.005)." (PMID 25181406, 2014). "Cognitive alterations are detected even before the patient's perception of his/her condition of hypoglycemia and are heterogeneous even for patients submitted to insulin-induced hypoglycemia under controlled conditions." (PMID 24790575, 2014).
Hypoglycemia (continued). "After 12 weeks of application, MDI-treated patients with T2DM had a higher total insulin dose requirement and hypoglycemia incidence and took longer to achieve the targeted glycemic control compared with the CSII-treated patients." (PMID 25187822, 2014). "Among insulin-naïve patients, incidence of hypoglycemia differed significantly depending on age, diabetic complications, estimated glomerular filtration rate (eGFR), and postprandial plasma glucose (P <0.05)." (PMID 24528773, 2014). "When combined with insulin, hypoglycemia is a major adverse effect and should be prevented by empiric dose reduction of mealtime insulin by 30%–50%." (PMID 26237392, 2014). "Typically, insulinoma manifests as Whipple’s triad, which includes hypoglycemia, elevated blood levels of insulin accompanied by a decrease in blood glucose levels to <50 mg/dl, and normalization of hypoglycemic signs following administration of sugar." (PMID 25202394, 2014). "Insulinoma is a rare tumor originating from insulin-synthetizing pancreatic beta cells which clinically manifests hypoglycemia." (PMID 25202394, 2014). "Successful insulin therapy involves a delicate balance between achieving adequate glycemic control while preventing hypoglycemia." (PMID 24092662, 2014). "This assay showed that ferret insulin diminished rapidly in the LOW group during hypoglycemia to sub-baseline levels." (PMID 24594704, 2014). "Obtaining optimal glycemic control while preventing hypoglycemia is a particular challenge clinicians face when treating geriatric patients, partly due to the difficulty in predicting the timing of peak insulin action." (PMID 23959960, 2014). "Insulin-induced hypoglycemia has been shown to increase ACTH, cortisol, growth hormone (GH), and catecholamine release in a number of studies." (PMID 24770625, 2014). "Samples collected during hypoglycemia showed a serum insulin of 134 (2.6 – 24.9 μU/ml) and C-peptide of 13.35 (1.1 – 4.4) ng/ml." (PMID 24741994, 2014). "People initiating insulin treatment with basal insulin experienced significantly lower rates of hypoglycaemia and less weight gain compared with prandial and premixed insulin regimens." (PMID 22998363, 2013). "The same trial also evaluated hypoglycaemia with neutral protamine Hagedorn (NPH) insulin (7.14 and 1.77 episodes per PYE, respectively) 6; these rates were higher than that with IDet, IGlar or IDeg." (PMID 23130654, 2013). "Events of insulin injections and blood glucose measurements are more or less interleaved loosely periodically over time; exercises and sometimes hypoglycemia occur occasionally." (PMID 24163813, 2013). "Copeptin, a marker for stress mirroring vasopressin concentrations, has been shown to increase upon insulin-induced hypoglycaemia in patients after transsphenoidal surgery of pituitary adenomas." (PMID 24023652, 2013). "The STAR1 trial of children using SAP therapy identified “failure to respond to high and low alarms, and/or appropriately dose and administer insulin,” as the main contributor to significantly higher rates of hypoglycemia." (PMID 23531400, 2013). "Congenital hyperinsulinism (CHI), previously known as persistent hyperinsulinemic hypoglycemia of infancy (PHHI, MIM256450), is characterized by severe hypoglycemia due to inappropriate insulin secretion from pancreatic β-cells." (PMID 23869231, 2013). "The drive toward more ambitious therapeutic targets, which often required the addition of insulin to oral drugs, was limited by the occurrence of hypoglycemia." (PMID 24348585, 2013). "In support of this, lipid peroxidation, an indirect marker of ROS production, is increased in response to insulin-hypoglycemia in the cortex." (PMID 23894333, 2013). "In conclusion, we find that Id2−/− mice exhibit altered feeding and locomotor rhythms, fasting hypoglycemia, sex- and age-dependent enhanced glucose tolerance and insulin sensitivity, and sex-dependent elevated glucose uptake in skeletal muscle and BAT." (PMID 24023810, 2013).
Hypoglycemia (continued). "Diagnosis can be made through demonstration of hypoglycemia and elevated plasma levels of insulin or C-peptide." (PMID 24455330, 2013). "Although the patient receives less than optimal insulin coverage at either end of the dosing schedule, the primary goal of preventing hypoglycemia is achieved while still giving insulin in a simple manner." (PMID 24360506, 2013). "A few months before the diagnosis of Addison's disease, it was necessary to decrease insulin doses in all these patients because of recurrent hypoglycemia (most often at night and in the early morning)." (PMID 23864857, 2013). "In the absence of glucagon counter-regulation, mutant mice would effectively have sufficient insulin to reduce glucose levels, thus providing a possible explanation for the hypoglycemia." (PMID 23977255, 2013). "The U.K. Hypoglycaemia Study Group found that mild hypoglycaemia in T2D patients during early insulin use was considerably less frequent than in T1D." (PMID 24053606, 2013). "Prediction of high or low glucose levels would allow caregivers to modify insulin infusion rates and, when applicable, administer exogenous dextrose or glucose to avoid hypoglycemia, thus further optimizing glycemic control." (PMID 23894489, 2013). "The CRR was evaluated in rats in response to acute insulin-induced hypoglycemia or via hypoglycemic-hyperinsulinemic clamps." (PMID 23894333, 2013). "Insulin (in all patients) and C-peptide (available in 11 patients) levels at the time of hypoglycemia ranged between 3.9 and 88 mIU/L and between 1.3 and 12 ng/mL, respectively." (PMID 24072082, 2013). "Congenital hyperinsulinism of infancy (CHI) is a rare disorder characterized by severe hypoglycemia due to inappropriate insulin secretion." (PMID 23869231, 2013). "In each trial comprising the meta-analysis, fasting plasma glucose and confirmed overall and nocturnal (00.01–05.59 h) hypoglycaemia were all numerically or significantly lower with insulin degludec vs. insulin glargine." (PMID 23199058, 2013). "A 2007 study reported the incidence of severe hypoglycaemia to be 110 episodes per 100 patient-years in patients with T1D treated with insulin for <5 years and 320 episodes per 100 patient-years in those treated for >15 years with insulin." (PMID 24053606, 2013). "In order to confirm these findings, we quantified the fluorescence intensity level of the ROS sensitive probe H2DCFDA (2′,7′-dichlorodihydrofluorescein diacetate) in the VMH of rats exposed to single or recurrent episodes of insulin-hypoglycemia." (PMID 23894333, 2013). "Hormone responses to two different stressors (insulin-induced hypoglycaemia and immune challenge induced by bacterial lipopolysaccharid) measured in 10-day-old rats were compared to those in adults." (PMID 24039750, 2013). "These higher initial BG levels in STZ rats combined with the similar rates of BG decline following insulin administration resulted in an increased latency to hypoglycemia and subsequent seizures in these animals." (PMID 24386156, 2013). "Note that in order to avoid hypoglycemia and to have a useful range for blood glucose to be decreased by insulin, we first gave a bolus of glucose in our IVITT experiments." (PMID 23383178, 2013). "Hypoglycemia reportedly occurs in up to 10% of patients taking insulin while traveling abroad, either during travel or in the first 24 hours after arrival." (PMID 24360506, 2013). "The level of H2DCFDA fluorescence intensity was significantly increased by a factor of 1.5±0.6 in response to a single episode of insulin-hypoglycemia." (PMID 23894333, 2013). "Up to 18% of the patients subjected to intensive insulin treatment have had episodes of hypoglycaemia." (PMID 23663747, 2013). "Pharmacologically stimulated GH levels were 0.15 and 0.39μg/L after insulin-induced hypoglycemia and arginine administration, respectively." (PMID 24377430, 2013).